FN1 (fibronectin 1)
Diseases named in the same sentence as FN1 in open-access papers (continued):
Sharing a sentence is not in itself a finding about the gene and the disease.
squamous cell carcinoma (8 papers, 2017 to 2025). A carcinoma arising from squamous epithelial cells. "As a risk factor, FN1 not only affected the prognosis of patients with HNSCC, but also affects other types of squamous cell carcinomas (lung squamous cell carcinoma and cervical squamous cell carcinoma) or other types of carcinomas in TCGA dataset." (PMID 36212151, 2022). "From GEPIA, patients harboring an increased expression of FN1 not only have a poor prognosis in HNSCC, but also in other 2 types of squamous cell carcinomas, such as lung squamous cell carcinoma and cervical squamous cell carcinoma." (PMID 36212151, 2022).
adenoma (7 papers, 2019 to 2025). A neoplasm arising from the epithelium. "Two panels, one consisting of Hp and LRG1 and one of Hp, LRG1, RBP4, and FN1, were identified for high‐risk adenomas and CRCs detection (sensitivity of 66% and 62%, respectively, at specificity of 95%)." (PMID 31784980, 2020). "Next to Hp, LAMP1, SYNE2, and ANXA6 were selected in the analysis for high‐risk adenomas, and also LRG1, RBP4, and FN1 for the high‐risk adenomas and CRCs." (PMID 31784980, 2020). "In the FGF23-producing adenoma sample (FGF_7), a fusion transcript involving exon 20 of FN1 and exon 11 of RET genes was detected." (PMID 41373459, 2025). "We identified a biomarker panel of Hp, LAMP1, SYNE2, and ANXA6 for identification of high‐risk adenomas and two biomarker panels – Hp and LRG1, as well as Hp, LRG1, RBP4, and FN1 – for identification of high‐risk adenomas and CRCs that outperformed hemoglobin." (PMID 31784980, 2020). "Immunohistochemical reaction for FN1 in adenoma was very focal and faint, present in rare stromal cells and capillaries." (PMID 33322258, 2020). "We conclude that Hp, LAMP1, SYNE2, LRG1, RBP4, FN1, and ANXA6 may be of value as stool biomarkers for early detection of high‐risk adenomas and CRCs." (PMID 31784980, 2020). "The difference in expression between adenoma and AEM was only significant for EPHA4 (p < 0.001) and FN1 (p = 0.009)." (PMID 33322258, 2020). "Significantly elevated N-cad, FN1, and VEGF may contribute to increased potential of FZD9-/- adenomas for progression to carcinoma." (PMID 35924166, 2022). "The aim of this study was to determine whether the expression of selected ECM-related genes (DCN, EPHA4, FN1, SPARC, SPON2, and SPP1) was similar in adenoma and AEM but differed from the expression in AEC and advanced carcinoma." (PMID 33322258, 2020). "However, on the protein level, FN1 showed discrete differences between AEM and AEC in comparison to adenoma." (PMID 33322258, 2020).
gastric adenocarcinoma (7 papers, 2019 to 2023). "Their obtained result demonstrated that the FN1 expression and SPARC in gastric adenocarcinoma tissues were found to be closely correlated to their poor prognosis." (PMID 35965624, 2022). "We identified THBS1, FN1, CALM1, COL4A1, CTGF, and IGFBP5 as potential inflammation-related targets for the treatment of gastric adenocarcinoma." (PMID 32801999, 2020). "However, the addition of FN1 to the COL1A1, COL5A1, and ITG4 Cox regression model decreased the poor prognostic impact of CAF in stomach adenocarcinoma." (PMID 35739492, 2022).
leukemia (7 papers, 2007 to 2024). A malignant (clonal) hematologic disorder, involving hematopoietic stem cells and characterized by the presence of primitive or atypical myeloid or lymphoid cells in the bone marrow and the blood. "In addition, out of two infant and two adult MLLr leukemia cell lines assayed in the presence of Fn1 and/or Fbln1, only the infant MLL::ENL ALL cell line KOPN-8 showed a decrease in viability, which was attributed to Fn1." (PMID 38555405, 2024). "We found both Vcam1 and, as previously highlighted, Fn1 and its antagonist Fbln1, to be higher abundant in FLEF relative to BMEF, suggesting a stronger impact of VLA-4/Vcam1 and VLA-4/Fn1 interactions in fetal-origin leukemia." (PMID 38555405, 2024). "Critically, differential dependency on the Igf2/Igf2r and Fn1/VLA-4 axes upon initiation of fetal- and adult-origin MLLr leukemia may represent an opportunity for targeting ontogeny-specific vulnerabilities in in utero-derived and adult-onset leukemia." (PMID 38555405, 2024).
mesenchymal tumors (7 papers, 2021 to 2025). "Here we describe the extremely rare entity of a “calcified chondroid mesenchymal neoplasm” (CCMN) with an FN1::FGFR2 fusion." (PMID 39404883, 2025). "Furthermore, even though some soft tissue chondromas are associated with FN1 gene rearrangements, they rarely can have moderate pleomorphism and typically do not exhibit hypercellular areas with cells resembling chondroblasts, which are characteristic of calcified chondroid mesenchymal tumor." (PMID 40585604, 2025). "The FN1::FGFR1 fusion gene is detected in phosphaturic mesenchymal tumors with paraneoplastic osteomalacia and FN1 has also been recently described as a novel fusion partner of ALK in an inflammatory myofibroblastic tumor." (PMID 36439507, 2022). "Fibroblasts from epithelial tumours contained more miR‐200 and expressed less ACTA2 and FN1 than those from mesenchymal tumours." (PMID 35595718, 2022). "The FN1 gene may provide an oligomerization domain of its constituent active promoter and encoding protein to overexpress and promote the activation of the FGFR1 kinase domain in mesenchymal tumors." (PMID 34567847, 2021). "Molecular diagnosis identified a fibronectin 1- fibroblast growth factor receptor 1 (FN1-FGFR1) gene fusion, encountered in over 50% of cases of phosphaturic mesenchymal tumors, therefore confirming the diagnosis." (PMID 39888445, 2025).
periodontitis (7 papers, 2012 to 2022). An acute or chronic inflammatory process that affects the tissues that surround and support the teeth. "Regarding the other target genes, the expression level of FN1 can reflect the progress of periodontitis or peri-implantitis." (PMID 34931168, 2021). "In subjects with well-controlled T2DM plus DL plus periodontitis versus HS, there were 3 DEG genes (BPTF, PDE3B, and FN1)." (PMID 36233348, 2022). "For FN1, the inclusion of EDB exon was preferentially observed in periodontitis tissues (7/10) compared with healthy tissues (3/8) tested." (PMID 27531006, 2016).
Peritoneal Fibrosis (7 papers, 2005 to 2025). Disorder characterized by a wide range of structural changes in PERITONEUM, resulting from fibrogenic or inflammatory processes. "Gal-1 expression in primary GC tissues has been shown to positively correlate with increased peritoneal collagen deposition, particularly types I and III, and fibronectin (FN1), which collectively contribute to peritoneal fibrosis." (PMID 40710343, 2025). "In TGF-β1-stimulated HPFBs, pro-fibrotic genes (COL1A1, COL1A2, ACTA2, CTGF, FN1, and TGFB1) exhibited higher expression than in controls, which are crucial targets of sildenafil and SB204741 against peritoneal fibrosis." (PMID 38322704, 2023).
type 2 diabetes (7 papers, 2015 to 2025). "In conclusion, this study shows that canagliflozin treatment decreases the plasma concentration of TNFR1, IL-6, MMP7 and FN1 in individuals with type 2 diabetes and elevated albuminuria." (PMID 31001673, 2019).
viral infection (7 papers, 2008 to 2022). "FN1 protein expression was also previously demonstrated to be dysregulated by viral infection; however, viruses are not included in this study due to sample collection methods." (PMID 35096646, 2021). "FN1 was also reportedly to facilitate viral infection through interaction with virus, such as HIV-1, in activated CD4+ T cells." (PMID 28591220, 2017). "Increases in pro-inflammatory mediators in viral infections, in turn, may further activate signaling pathways involved in fibrosis, characterized by excessive deposition of ECM proteins, mostly fibronectin 1 (FN1) and type I collagen (COL1A1)." (PMID 34512638, 2021).
cardiac hypertrophy (6 papers, 2013 to 2024). "Reactive oxygen species (ROS) have been shown to up-regulate expression of profibrotic genes, such as col2a1, col1a1, and fn1, thereby resulting in direct extracellular matrix deposition in a transgenic mouse model, and resulting in cardiac hypertrophy." (PMID 23922799, 2013). "However, the results showed that, despite that the mice clearly exhibited cardiac hypertrophy and fibrosis, the expressions of FN1 and CTGF were not elevated, while the DCN expression was slightly increased in the interstitial region (see Section 3)." (PMID 37766635, 2024). "Unlike TGFβ1, it is unclear whether increased FN1 expression is a mechanism or consequence of fibrosis; however, it has been shown in transgenic animals that systemic FN1 knockout prevents pressure-overload induced cardiac hypertrophy and fibrosis." (PMID 31920673, 2019).
Cirrhosis (6 papers, 2014 to 2025). A chronic disorder of the liver in which liver tissue becomes scarred and is partially replaced by regenerative nodules and fibrotic tissue resulting in loss of liver function. "For example, the persistent expression of the HBV x antigen (HBxAg) is correlated with the development of fibrosis and cirrhosis during CHB, as it can activate fibronectin-1 (FN-1) gene, through the induction of the nuclear factor kappa B (NF-kappa B or NFkB)." (PMID 29713327, 2018).
invasive breast carcinoma (6 papers, 2011 to 2024). A carcinoma that infiltrates the breast parenchyma. "Stromal reaction to invasive breast carcinoma was associated with increased expression of genes encoding ECM components, proteolytic enzymes and adhesion receptors, including COL11A1, COL10A1, COMP, MMP11, FN1 and MFAP2, consistent with the abundant stromal remodeling observed by histology." (PMID 21611158, 2011). "For example, featured genes such as COL1A1, COL5A1, FN1, and ACTB are involved in invasive breast carcinoma and osteogenesis imperfecta, a heritable bone fragility disorder associated with short stature and abnormalities." (PMID 34858485, 2021).
ischemic stroke (6 papers, 2016 to 2025). A stroke disorder caused by obstruction of blood flow to the brain, due to thrombotic (local blood clot formation) or embolic (due to a blood clot or other material traveling from another site) event. "FN1 has been implicated in ischemic stroke by promoting inflammation, participating in repair mechanisms, and regulating cell functions in the bone marrow microenvironment." (PMID 40299522, 2025). "Many of the identified genes, including TLR2, TLR3, TLR9, GRN, COL1A1, FN1, and LAMB1, were reported as upregulated genes in previous reports of ischemic stroke." (PMID 35887140, 2022). "Our results showed that FN1 and VTN levels were higher in ischemic stroke patients than in healthy controls, which was consistent with previous studies." (PMID 32466277, 2020). "It has also been reported that microglia activated by FN1 and VTN promote the progression of ischemic stroke." (PMID 32466277, 2020). "C1QA, FGG, FN1, and VWF could therefore be involved in atherogenesis progression in patients with CSC ischaemic stroke." (PMID 34356850, 2021). "FN1 and VTN activate microglia when brain damage occurs due to conditions such as ischemic stroke." (PMID 32466277, 2020).
metastatic cancer (6 papers, 2015 to 2023). A carcinoma which has spread from the original site of growth to another anatomic site. "Metastatic cancer-1 cells highly expressed mesenchymal markers (e.g., VIM, FN1, and COL1A1), typical of EMT, whereas metastatic cancer-2 cells highly expressed partial EMT (p-EMT) signature genes (e.g., LAMC2, PDPN, and INHBA), indicative of a p-EMT phenotype." (PMID 37853464, 2023). "Hypoxic MB-KO cells showed upregulation of FN1, a glycoprotein ECM component of the mesenchymal compartment that is not normally expressed by breast tissue, thus indicating the switching to an increased capacity of invasive and metastatic cancer cell behavior and induced EMT in MCF7 cells." (PMID 36232784, 2022).
metastatic melanoma (6 papers, 2006 to 2025). A melanoma that has spread from its primary site to another anatomic site. "Furthermore, FN1 is highly expressed both in metastatic melanoma and OSCC cells." (PMID 32886718, 2020).
amoebiasis (5 papers, 2013 to 2022). "In addition, the up-regulated DEGs were significantly enriched in 12 pathways such as NF-kappa B signaling pathway including LYN, LY96, CCL4, CD14; ECM-receptor interaction pathway including CD44, COL6A3, COL1A2, FN1 and Amoebiasis pathway including COL1A2, ITGB2, CD14, FN1." (PMID 31355054, 2019). "FN1 and COL1A2 were both enriched in PI3K-Akt signaling pathway (hsa04151), amoebiasis (hsa05146), and focal adhesion (hsa04510)." (PMID 36398072, 2022). "Further analysis shows that anakinra works by binding receptor IL1R, which may influence multiple pathways like osteoclast differentiation pathway and amoebiasis pathway, affecting CD genes NCF4 and FN1 respectively." (PMID 24564553, 2013).
Arthritis (5 papers, 2012 to 2022). Inflammation of a joint. "FN1 is a member of the FN family and plays a variety of biological functions in tumors, atherosclerosis, arthritis, and other diseases." (PMID 34276798, 2021).
Infertility (5 papers, 2019 to 2025). "An in-depth functional analysis of sperm proteins revealed that SPA17 and fibronectin (FN1) associated with reproductive system development and function were underexpressed in normozoospermic infertile men." (PMID 31336797, 2019). "FN1 was downregulated in CCs of infertile polycystic ovary syndrome women." (PMID 40497967, 2025).
malignant glioma (5 papers, 2013 to 2021). A grade III or grade IV glioma arising from the central nervous system. "EMT, as a key factor of malignant glioma invasion enhancement, can be characterized by an increase in the expression of biomarkers, such as CDH2, VIM, FN1, SNAI1, SNAI2, ACTA2, and so on." (PMID 34034744, 2021).
oral cancer (5 papers, 2021 to 2025). "With the use of bioinformatics analysis of the gene expression profile of metastatic and non-metastatic lymph nodes and original tumors, we identified a novel oral cancer metastatic gene signature, FN1, CXCL8, and MMP9." (PMID 37640804, 2023). "By translating the most significantly expressed gene matrix into clinical datasets of oral cancer tissues, we showed that the summed expression of FN1, TGFB2, TGFBR2, and TGFBI, dubbed the CAF index, is a poor indicator of overall survival for oral cancer (n=40) and the PANCAN (n=9,356) cohorts." (PMID 34869001, 2021). "Moreover, FN1 could affect the immune response in oral cancer cells." (PMID 37936719, 2023). "The three (FAP, FN1, and MMP1) overexpressed genes show a significant potentiality for oral cancer development." (PMID 37936719, 2023). "We chose three overexpressed genes (FAP, FN1, and MMP1) that could have potential regarding their presence in oral cancer patients." (PMID 37936719, 2023).
spondylometaphyseal dysplasia (5 papers, 2020 to 2026). Spondylometaphyseal dysplasias are a heterogeneous group of disorders associated with walking and growth disturbances that become evident during the second year of life. "Mutations in the human FN1 gene are associated with the skeletal disease spondylometaphyseal dysplasia with “corner fractures.”17 Such mutations often affect cysteine residues." (PMID 41399493, 2025).
Ureteral obstruction (5 papers, 2016 to 2025). Obstruction of the flow of urine through the ureter. "Administration of ICG-001 abolished the expression of Fn1 and Inhba which was induced by the ureteral obstruction and reduced the expression of the Wnt target gene, Snai1." (PMID 30075015, 2018). "Moreover, unilateral ureteral obstruction (UUO)-induced CKD models increased levels of TGF-β and the renal fibrotic genes Col1a1 and Fibronectin-1." (PMID 40141345, 2025).
aneurysm (4 papers, 2012 to 2025). Bulging or ballooning in an area of an artery secondary to arterial wall weakening. "In our other dataset (GSE54083), we were surprised to find that the expression of CDH11, SPARC, FN1, and FSTL1 in unruptured aneurysms was significantly increased, while WNT11, PCDH9, and GPC3 expression levels were relatively low." (PMID 34997174, 2022). "It was found that the expression levels of CDH11, SPARC, FN1, and FSTL1 genes in unruptured aneurysms were higher than those in healthy samples, while the expression levels of WNT11, PCDH9, and GPC3 in unruptured aneurysms were lower than those in healthy samples." (PMID 34997174, 2022).
chondrosarcoma (4 papers, 2012 to 2025). A malignant cartilaginous matrix-producing mesenchymal neoplasm arising from the bone and soft tissue. "Recently, it was reported that the fibronectin 1 and activin receptor 2A fusion gene identified in chondrosarcoma were also identified in SC." (PMID 35457572, 2022). "In concordance with our data, FN1 was also upregulated in different metastatic chondrosarcomas." (PMID 22448124, 2012). "Caution is warranted since i) FN1 and ACVR2A rearrangements in SC are reportedly present in only 57% of cases, and ii) these rearrangements were reported in 75% of cases with chondrosarcoma secondary to SC." (PMID 38179177, 2023).
diffuse large B-cell lymphoma (4 papers, 2013 to 2022). "Previous research found DBH-AS1 recruited BUD13 enhancing FN1 stability, and promoted cell proliferation, migration, and invasion in diffuse large B-cell lymphoma." (PMID 36463205, 2022). "Interestingly, FN1 also belongs to the gene signature predicting longer survival in diffuse large B-cell lymphomas treated with CHOP." (PMID 34771686, 2021).
interstitial lung disease (4 papers, 2017 to 2025). A diverse group of lung diseases that affect the lung parenchyma. "In addition, single cell RNA sequencing analysis of tissue-resident CD14+ pulmonary macrophages demonstrated activated profibrotic signature with the elevated FN1 expression in SSc patients with interstitial lung disease." (PMID 34504485, 2021).
mastitis (4 papers, 2010 to 2021). Inflammation of breast tissue during lactation or postpartum due to an obstructed duct or infection. "In summary, TMT analyses elucidated the role of A2M, Itgb2, Thbs1, Fn1, ITIH4 and other proteins in the host innate response to S. aureus-induced mastitis." (PMID 32365127, 2020).
medullary thyroid cancer (4 papers, 2020 to 2023). "Low fibronectin 1 (FN1) expression in tumorous tissues was an independent worse prognostic factor for progression-free survival in sporadic medullary thyroid carcinoma." (PMID 32714651, 2020). "For example, FN1 was highly expressed in sporadic medullary thyroid cancer tissues, and the immunohistochemical score of FN1 in tumor tissues was negatively correlated with American Joint Committee on Cancer stage, tumor histopathological typing and lymph node classification." (PMID 34567847, 2021).
nephrolithiasis (4 papers, 2017 to 2026). The presence of a calculus in the pelvis of the kidney; this is most often composed of mineral salts and proteins. "The child’s mother had a history of hematuria and nephrolithiasis for 5 years and she displayed the same heterozygous mutation of the FN1 gene." (PMID 39859354, 2025). "Genes encoding for Runx1, Runx2, KRT 18, KRT 8, VIM, Fn-1, Col1a1 and Col1a2 were up regulated during hyperoxaluric conditions and further increased after crystal deposition or nephrolithiasis." (PMID 29091707, 2017).
psoriasis (4 papers, 2011 to 2024). An autoimmune condition characterized by red, well-delineated plaques with silvery scales that are usually on the extensor surfaces and scalp. "In psoriasis, FN1 was highly expressed in synovial biopsies suggesting its role in the pathogenesis of the disease." (PMID 39662827, 2024). "FN1 has been shown to be an angiogenic cytokine involved in angiogenesis during several pathological processes, such as psoriasis, diabetic retinopathy, and cancer." (PMID 21843314, 2011).